MS4A7 (membrane spanning 4-domains A7)
Description:
May be involved in signal transduction as a component of a multimeric receptor complex.
Synonyms: 4SPAN2; CD20L4; CFFM4; MS4A8
Tractability: Antibody: UniProt predicts a signal peptide or a membrane-spanning region; its Gene Ontology location is reachable by antibodies, with medium confidence.
Gene: Protein-coding gene on chromosome 11 (60,378,482 to 60,395,951, forward strand). Ensembl gene ENSG00000166927.
Subcellular location: Membrane
Gene Ontology:
Molecular function: protein binding
Biological process: cell surface receptor signaling pathway
Cellular component: trans-Golgi network; plasma membrane; membrane
Genetic constraint (gnomAD): Loss-of-function variants: 13 observed, 14.73 expected, observed/expected ratio (o/e) 0.88, 90% interval 0.57 to 1.4. The upper end of that interval is the gene's LOEUF score, 1.4, which puts it in group 5 of 6, group 1 being the genes least tolerant of losing a copy. Missense variants: 196 observed, 227.4 expected, observed/expected ratio (o/e) 0.86, 90% interval 0.77 to 0.97. Synonymous variants: 88 observed, 90.94 expected, observed/expected ratio (o/e) 0.97, 90% interval 0.81 to 1.15.
Homologues: Orthologues: chimpanzee MS4A7 (99% identical), macaque MS4A7 (93% identical), dog MS4A7 (69% identical), pig MS4A7 (67% identical), mouse Ms4a7 (52% identical), rat Ms4a7 (48% identical), zebrafish ms4a17a.10 (20% identical), zebrafish ms4a17a.11 (20% identical), zebrafish ms4a17a.16 (19% identical), zebrafish ms4a17a.1 (19% identical), zebrafish ms4a17a.17 (19% identical), zebrafish ms4a17a.3 (19% identical), and 19 more. Paralogues in human: MS4A6A (34% identical), MS4A4A (22% identical), MS4A15 (22% identical), MS4A8 (21% identical), MS4A1 (20% identical), MS4A2 (20% identical), MS4A12 (20% identical), MS4A14 (20% identical), MS4A3 (19% identical), MS4A6E (19% identical), MS4A5 (18% identical), MS4A18 (18% identical), and 4 more.
Diseases named in the same sentence as MS4A7 in open-access papers:
MS4A7 is named in the same sentence as 22 diseases in open-access papers, as found by Europe PMC text mining. Sharing a sentence is not in itself a finding about the gene and the disease. The quoted sentences say what the papers report.
glioma (4 papers, 2022 to 2024). A benign or malignant brain and spinal cord tumor that arises from glial cells (astrocytes, oligodendrocytes, ependymal cells). "The present study uncovered MS4A7-s, a short isoform of MS4A7, as a key regulator in glioma-associated macrophages (GAMs), which promotes the M2 polarization and predicts poor clinical outcome." (PMID 36944954, 2023). "Combining TCGA, GEO (GSE147352) and GTEx data, we found that expression of MS4A7 was higher in glioma samples than that in normal regions and positively correlated with glioma grading." (PMID 36944954, 2023). "In conclusion, MS4A4A, MS4A4E, MS4A6A, MS4A7, TMEM176A, and TMEM176B may act as potential diagnostic or prognostic biomarkers in glioma and play a role in forming the immune microenvironment in gliomas." (PMID 35734424, 2022). "Studies have shown that MS4A7 has a particular prognostic value in ovarian cancer and glioma." (PMID 36401283, 2022). "The genes analyzed included HLA‐DQA1, HLA‐DQB1, HLA‐DMB, LY86, MS4A7, FOLR2, and MS4A4A in glioma patients." (PMID 38997808, 2024). "In TCGA data, the expression level of MS4A4A, MS4A4E, MS4A6A, MS4A7, TMEM176A, and TMEM176B in IDH wild-type glioma was elevated." (PMID 35734424, 2022). "Using bioinformatics analysis methods based on the data from public databases, we found that the expression of MS4A4A, MS4A4E, MS4A6A, MS4A7, TMEM176A, and TMEM176B was significantly overexpressed in glioma tissues compared with that of normal tissues." (PMID 35734424, 2022). "Therefore, these preliminary results indicate that MS4A4A, MS4A4E, MS4A6A, MS4A7, TMEM176A, and TMEM176B are potential prognostic factors for glioma." (PMID 35734424, 2022). "In TCGA data, the expression level of MS4A4A, MS4A4E, MS4A6A, MS4A7, TMEM176A, and TMEM176B in 1p/19q non-codel glioma was elevated." (PMID 35734424, 2022).
gastric cancer (2 papers, 2022 to 2023). A primary or metastatic malignant neoplasm involving the stomach. "In addition, the low expression of MS4A7 was found to be correlated with better overall survival (OS) in gastric cancer patients." (PMID 37031243, 2023).
glioblastoma (2 papers, 2023 to 2024). The most malignant astrocytic tumor (WHO grade IV). "Mass cytometry with additional markers, demonstrated unchanged levels of CD206 but reduced CD169, MS4A7 and CD64 in glioblastoma-associated CAMs." (PMID 38123840, 2024).
ovarian carcinoma (2 papers, 2022 to 2023). A malignant neoplasm originating from the surface ovarian epithelium. "Single-cell sequencing findings have confirmed that MS4A7 is highly expressed in some macrophages, and can be used as an immune signature to predict ovarian cancer prognoses." (PMID 36999020, 2023).
Arthritis (1 paper, 2006). Inflammation of a joint. "Although the upregulation of Ms4a7, Ms4a4d, Ms4a6d, and Ms4a6c expression in chromosome 19, 11-Mb locus (#14) was also observed in these models of RA, the roles of these molecules in the development of arthritis are not yet known." (PMID 16805906, 2006).
breast carcinoma (1 paper, 2024). "In addition, the other three host genes (GNA12, BTRC, and MS4A7) correlated to lncRNA expression have been demonstrated to be associated with cancer progression, and specifically, the enhancement of BTRC expression could facilitate M2 macrophage polarization in breast cancer." (PMID 39126025, 2024).
epilepsy (1 paper, 2025). A brain disorder characterized by episodes of abnormally increased neuronal discharge resulting in transient episodes of sensory or motor neurological dysfunction, or psychic dysfunction. "Our results revealed a marked upregulation of MS4A4A, MS4A6A, MS4A7, and MS4A14 in lesional tissues of FEAT epilepsy patients relative to perilesional tissues." (PMID 40349168, 2025).
lung adenocarcinoma (1 paper, 2023). A carcinoma that arises from the lung and is characterized by the presence of malignant glandular epithelial cells. "According to the Kaplan-Meier curve, patients with lung adenocarcinoma having poor expression of MS4A2, MS4A7, MS4A14, and MS4A15 had a low overall survival rate." (PMID 37533433, 2023).
Pleural effusion (1 paper, 2025). The presence of an excessive amount of fluid in the pleural cavity. "We also identified pleural effusion predictive gene signatures, including TMPRSS3, MS4A7, NAPSA, and IGFBP2, while liver metastasis predictive markers included WFDC2, HSPB1, COX6C, APOE, and TUBA1A." (PMID 39955556, 2025).
rheumatoid arthritis (1 paper, 2022). A chronic, systemic autoimmune disorder characterized by inflammation in the synovial membranes and articular surfaces. "Consistently with in vitro findings, MS4A4A and MS4A7 were expressed in tissue Mφs from COVID‐19 and rheumatoid arthritis patients." (PMID 34346525, 2022).
triple-negative breast carcinoma (1 paper, 2024). An invasive breast carcinoma which is negative for expression of estrogen receptor (ER), progesterone receptor (PR), and human epidermal growth factor receptor 2 (HER2). "In triple-negative breast cancer (TNBC), MS4A7 has been identified as a prognostic factor, and a predictive model that incorporates the MS4A7, SPARC, and CD300C genes has demonstrated strong prognostic accuracy." (PMID 39717774, 2024).
tumor (13 papers, 2022 to 2025). "scRNA-seq and scTCR-seq analysis show that cKO mice exhibit reduced immunosuppressive Ms4a7+C1qa+ tumor-associated macrophages (TAMs) but increased intratumoral IFN-γ+CD8+ T cell infiltration and expansion." (PMID 41431992, 2025). "Recent research suggests that MS4A7 is highly expressed in tumor‐associated macrophages (TAMs), where it modulates the tumor microenvironment and immune evasion, potentially influencing cancer progression." (PMID 40522023, 2025). "These interactions suggest that MS4A7+ macrophages play a pivotal role in immune modulation, influencing both tumor progression and therapeutic response." (PMID 40356720, 2025). "Compared to adjacent normal brain tissue, MS4A7 was typically enriched in GAMs within the tumor mass, with close relation to macrophage/microglia marker CD68 and M2 marker CD163." (PMID 36944954, 2023). "To further investigate the mechanism by which MS4A7-s affects the polarization phenotype of GAMs and exerts tumor-promoting effects, we extracted total RNA from control, MS4A7-s OE and MS4A7-l OE groups of HMC3 cells for RNA-seq." (PMID 36944954, 2023). "Our research found that MS4A7 mainly mediates most immune-related pathways, such as immune receptor activity, but MS4A7 is down-regulated in tumor tissues, and its low expression levels indicate a worse prognosis." (PMID 36401283, 2022). "Among them, Module2 (highly express RNASE1, C1QA, CD163, CD14, C1QC, FCGRT, and MS4A7) and Module10 (highly express APOC1, CTSB, CTSL, and TYROBP) are more likely to display the characteristics of tumor-associated macrophages (TAMs)." (PMID 35990663, 2022). "Targeting MS4A7 or modulating macrophage function may enhance the anti-tumor immune response and improve patient outcomes." (PMID 40356720, 2025). "It is speculated that the tumor produces immune tolerance by down-regulating the expression of MS4A7, leading to a worse prognosis." (PMID 36401283, 2022). "Comparing gene expression in the immune cell infiltrate between the two primary tumours, the greatest number of DEGs was seen in the macrophage (CD86 and MS4A7-expressing) cluster." (PMID 40438247, 2025). "The results indicated an increase in MS4A4A, HLA‐DMB, LY86, MS4A7, and FOLR2 expression in GBM tumor samples compared to normal tissue samples (n = 706)." (PMID 38997808, 2024). "According to the tumor grades, in TCGA database, compared with WHO II and III, the transcription levels of MS4A4A, MS4A4E, MS4A6A, MS4A7, TMEM176A, and TMEM176B were the highest in WHO IV." (PMID 35734424, 2022). "Protein levels of MS4A10, MS4A8, MS4A7, PCNA, BAX, Bcl-2, Caspase-3, and cleaved Caspase-3 were measured in tumor tissues." (PMID 36438804, 2022). "The ratio of MS4A7-s’ expression levels to the sum of these two isoforms’ expression levels was not significantly different between tumor tissue and adjacent normal brain tissue." (PMID 36944954, 2023).
cancer (4 papers, 2022 to 2025). A tumor composed of atypical neoplastic, often pleomorphic cells that invade other tissues. "Beyond its involvement in inflammation, MS4A7 has also been implicated in several diseases, including neurodegenerative disorders, cancers, and metabolic conditions." (PMID 40522023, 2025).
MS4A7 also shares sentences with these, for which no sentence is quoted: acute myeloid leukemia (1 paper); Erythema (1); esophageal carcinoma (1); low grade glioma (1); melanoma (1); pancreatic adenocarcinoma (1); Sepsis (1); skin cutaneous melanoma (1); spinal cord injury (1).